ABCA4 (ATP binding cassette subfamily A member 4)
Diseases named in the same sentence as ABCA4 in open-access papers (continued):
Sharing a sentence is not in itself a finding about the gene and the disease.
Stargardt disease (continued). "Stargardt disease is a progressive, autosomal recessive disease which is caused by mutations in the ABCA4 gene, an ATP-Binding Cassette transport gene superfamily member, which contains 50 exons and is on the short arm of chromosome number one (1P)." (PMID 37600916, 2023). "This double-masked, placebo-controlled trial randomized 50 patients with Stargardt’s disease caused by the ABCA4 mutation into the treatment and placebo groups at a 2:1 ratio." (PMID 38136230, 2023). "ABCA4, the gene implicated in Stargardt disease (STGD1), contains 50 exons, of which 17 contain multiples of three nucleotides." (PMID 37587475, 2023). "It is of note that Lumacaftor has been shown to rescue the processing and cell surface expression of ABCA4 mutants associated with Stargardt Disease; however, by western blot we previously found that it did not increase the expression of mutant Best1." (PMID 37110551, 2023). "Family F1865 with Stargardt disease is a good example where the ABCA4 variant NM_000350.3:c.5882 G > A;p.(Gly1961 Glu) was initially dismissed because of the high frequency in gnomAD in addition to the presence of unaffected homozygous individuals." (PMID 37644014, 2023). "The potential of R-AF for quantitative analysis of lipofuscin-associated AF is demonstrated in a patient with ABCA4-related retinopathy (Stargardt disease)." (PMID 37336979, 2023). "ABCA4-RD and Stargardt disease is confined to the retina, but CLN3-associated Batten disease is a devastating diagnosis because of the systemic and neurological manifestations that typically result in a short life expectancy." (PMID 38066771, 2023). "smMIPs have been used to provide a molecular diagnosis to patients with ABCA4-associated Stargardt disease (STGD1) and to capture the entirety of ABCA4 in large cohorts of patients at a high depth of coverage, up to an average of ~700× in large cohorts." (PMID 36672932, 2023). "Mutations in the ABCA4 gene are implicated in Stargardt disease (STGD1), RP, and several other retinal dystrophies." (PMID 36836473, 2023). "Functional impairment caused by ABCA4 sequence variations is the leading cause of autosomal recessive inherited retinal disorders, including Stargardt disease, retinitis pigmentosa, and cone-rod dystrophy." (PMID 37108442, 2023). "Biallelic variants in ABCA4 are the cause of Stargardt disease (STGD1), which is the most frequent heritable macular degeneration." (PMID 40225145, 2023). "Biallelic variants in ABCA4 cause Stargardt disease (STGD1), the most frequent heritable macular disease." (PMID 40225145, 2023). "While ABCA4 defects can cause RP, they more typically cause an inherited macular degeneration (Stargardt disease), with varying degrees of full-field cone or cone-rod dystrophy." (PMID 37261916, 2023). "Mutations of the ABCA4 gene are the cause of retinal degenerations called “ABCA4-retinopathies”, with the most prevalently inherited macular dystrophy called Stargardt disease (STGD1; MIM# 248200)." (PMID 37175983, 2023). "The C1490Y is a recessive pathogenic variant in ABCA4 that is associated with Stargardt macular dystrophy." (PMID 36836473, 2023). "It is notable that an allied experimental approach has been explored previously for ABCA4-linked Stargardt disease (STGD1) in genetically modified mice." (PMID 36835257, 2023). "Stargardt disease (STGD1) is a rare autosomal recessively inherited macular dystrophy with central vision loss caused by biallelic mutations in the ATP-binding cassette transporter (ABCA4) gene." (PMID 35262734, 2022). "Mutations in the ABCA4 gene are responsible for recessive Stargardt disease (STGD1), a juvenile maculopathy that shares many clinical and pathologic features with dry-form of age-related macular degeneration (AMD)." (PMID 36359858, 2022). "Many genetic variants of ABCA4 are associated with various forms of retinal dystrophy, including Stargardt disease, retinitis pigmentosa, and cone-rod dystrophy." (PMID 36566289, 2022).
Stargardt disease (continued). "Further investigations obtained other variants that declare the case possible to be a career for ABCA4-related disorders: Stargardt disease, Cone-rod dystrophy 3, and retinal dystrophy." (PMID 36239105, 2022). "Stargardt disease is an inherited retinal disease caused by biallelic mutations in the ABCA4 gene, many of which affect ABCA4 splicing." (PMID 36552712, 2022). "For some diseases, cryptic splicing variants are in fact very common such as POLR3A variants for recessive spastic ataxia, ATM variants for Ataxia telangiectasia, ABCA4 for Stargardt diseases, and NF1 variants for neurofibromatosis." (PMID 34591693, 2022). "For example, the transport activities of p.Gly863Ala, p.Asn965Ser, p.Lys969Met, and p.Lys1978Met variants found in Stargardt disease were significantly reduced compared with that of the wild-type ABCA4 following overexpression in HEK-293T cells." (PMID 36566289, 2022). "Our findings suggest that ABCA4 variants in patients with Stargardt disease affect ABCA4 expression." (PMID 36566289, 2022). "The most prevalent disease causative gene associated with Stargardt disease is ABCA4, which clears retinal from photoreceptor disk membranes and RPE endolysosomal membranes." (PMID 36138817, 2022). "Here, we report the results of mutation screening of six exons of the ABCA4 gene in 18 unrelated Iranian Stargardt disease patients." (PMID 35194496, 2022). "About ABCA4 variants found in Stargardt disease, macular and cone dystrophies were predominant in Asian (42%) and European (21%) patients." (PMID 35836572, 2022). "In this study, we functionally characterized ABCA4 variants found in Korean patients with Stargardt disease or variants of the ABCA4 promoter region." (PMID 36566289, 2022). "ABCA4 pathogenic variants were found in eight patients, all of whom were diagnosed as Stargardt disease." (PMID 36011402, 2022). "Mutations in the ABCA4 gene are considered the most common aetiology for the occurrence of Stargardt's disease." (PMID 36457622, 2022). "Recessive Stargardt disease (STGD1) is an inherited retinopathy caused by mutations in the ABCA4 gene." (PMID 36359858, 2022). "Two of the studied ABCA7 mutants, p.A845V and p.R1932C, are in conserved amino acid residues and mutations at these residues in ABCA1 or ABCA4 are known to cause Tangier disease or Stargardt disease respectively." (PMID 35361255, 2022). "ABCA4 mutation is revealed with a granular pattern with punctate spots in the periphery, which resembles Stargardt disease." (PMID 36362067, 2022). "Various strategies have been exploited to ameliorate the toxic effects of retinoid intermediates and byproducts in the visual cycle, with a particular focus on Stargardt disease caused by ABCA4 mutations." (PMID 36138817, 2022). "All of the patients with Stargardt disease that had positive genetic testing demonstrated pathogenic variants in the ABCA4 gene." (PMID 36011402, 2022). "ABCA4 mutations are responsible for Stargardt disease, but different variants on that gene have a wide range of possible phenotypical manifestations, among which is included AMD." (PMID 36362067, 2022). "The NCSS variant c.161G>A, which has been previously associated with Stargardt disease, demonstrates the complexity of the ABCA4 genetic analysis." (PMID 33673358, 2021). "Stargardt disease is the most prevalent inherited macular dystrophy, usually presented as an autosomal recessive condition caused by mutations in the ABCA4 gene." (PMID 33673358, 2021). "A 43-year-old female with bull’s eye maculopathy, whose sister was diagnosed with Stargardt disease previously at another centre, was found to have a single ABCA4 variant." (PMID 33836713, 2021). "Owing to its essential function in the visual cycle, mutations in ABCA4 are also associated with retinitis pigmentosa-19, cone-rod dystrophy type 3, early-onset severe retinal dystrophy, fundus flavimaculatus, and other macular degenerative diseases." (PMID 33556440, 2021).
Stargardt disease (continued). "Mutations in the ABCA4 gene are a common cause of Stargardt disease; however, other retinal phenotypes have also been associated with mutations in this gene." (PMID 34008801, 2021). "In the human retina, mutations in the ABCA4 gene can lead to Stargardt’s disease, and are associated with increased risk of a certain subtype of retinitis pigmentosa and age-related macular degeneration." (PMID 34068492, 2021). "A significant proportion of these patients, especially those suspected to have Stargardt disease/cone–rod dystrophy, bear pathogenic variants in the ABCA4 gene." (PMID 34946832, 2021). "WES Results: WES revealed a single previously known recessive pathogenic variant c.4469 G > A:p.(C1490Y) in ABCA4 in Stargardt macular dystrophy (OMIM 248200)." (PMID 33776059, 2021). "Studies have shown that ABCA4 mutations can cause retinal degenerative diseases, such as Stargardt’s diseases and retinitis pigmentosa." (PMID 34592902, 2021). "The most common mutations causing Stargardt Disease affect the ABCA4 (ATP Binding Cassette subfamily A member 4) gene." (PMID 33546345, 2021). "ABCA4 variants are known to be a major cause of Stargardt disease as well as some autosomal recessive RP." (PMID 33608557, 2021). "The discovery of novel intronic variants in the ABCA4 locus has contributed significantly to solving the missing heritability in Stargardt disease (STGD1)." (PMID 33924840, 2021). "The classical form of Stargardt disease is caused by homozygous or compound heterozygous pathogenic variants in the adenosine triphosphate (ATP)-binding cassette (ABC) transporter 4 (ABCA4) gene." (PMID 34073554, 2021). "Sometimes these children are erroneously diagnosed with Stargardt disease (ABCA4-associated retinopathy), but the visual loss is usually more profound and rapidly progressive than that seen in Stargardt disease." (PMID 34127841, 2021). "Deep intronic variants in the ABCA4 gene causing Stargardt disease and the GUCY2D gene causing Leber congenital amaurosis were also identified." (PMID 32000842, 2020). "ABCA4 gene mutations are the cause of a spectrum of ABCA4 retinopathies, and the most common juvenile macular degeneration is called Stargardt disease." (PMID 32413971, 2020). "Mutations of the ABCA4 gene are the cause of more than 95% of cases of Stargardt disease (STGD)—the most common form of inherited juvenile macular degeneration—as well as other monogenic retinal diseases, the so-called ABCA4 retinopathies." (PMID 32413971, 2020). "They showed that fAAV2/5 ABCA4 delivery led to a stable improvement of morphological abnormalities and retinal dysfunction associated with a mouse model of Stargardt disease." (PMID 32733204, 2020). "Enhanced accumulation of lipofuscin is believed to be the sole etiological factor in monogenic Stargardt disease, a genetic form of macular degeneration caused by mutations in the ABCA4 gene." (PMID 31978148, 2020). "Two genes that do not fit in a conventional rAAV gene cassette (MYO7A linked to Usher syndrome Type 1B and ABCA4 to Stargardt disease) have been delivered to the retina by recombinant lentiviral expression vectors instead." (PMID 32545533, 2020). "Stargardt disease is a progressive retinal disorder caused by bi-allelic mutations in the ABCA4 gene that encodes the ATP-binding cassette, subfamily A, member 4 transporter protein." (PMID 32653833, 2020). "ABCA4-related retinopathy, one of the most common monogenic causes for retinal degeneration, is known for a broad phenotypic spectrum, ranging from mild Stargardt disease to severe cone–rod dystrophy." (PMID 32013026, 2020). "Our data illustrate the importance of intronic variants in ABCA4 and expand the therapeutic possibilities for overcoming splicing defects in Stargardt disease." (PMID 32653833, 2020). "Recently, up to nine antisense-oligonucleotide variants were identified for the treatment of Stargardt disease caused by the intronic c.4539 + 2001G >A mutation in the large ABCA4 gene." (PMID 32733204, 2020).
Stargardt disease (continued). "We performed cDNA sequencing to reveal the presence of full-length ABCA4 transcripts and analyzed ABCA4 transcripts from three patients with Stargardt disease carrying different splice-site ABCA4 variants: c.5312+1G>A, c.5312+2T>G and c.5836-3C>A." (PMID 32413971, 2020). "ABCA4, which harbors causative mutations leading to Stargardt disease, was enriched in foveal photoreceptors; EFEMP1, implicated in Doyne Honeycomb Dystrophy, was predominantly expressed in foveal Müller glia." (PMID 32555229, 2020). "Recessive Stargardt disease (STGD1) or ABCA4-related retinopathy is an important cause of inherited retinal degeneration and loss of vision in early life." (PMID 32751377, 2020). "The applicability of the hair follicle model was confirmed by the analysis of three different splice-site ABCA4 variants from patients with Stargardt disease." (PMID 32413971, 2020). "We predict that the intronic mutation, c.5461-10T > C in ABCA4, contributes to the Stargardt disease in Family 4100." (PMID 33425925, 2020). "ABCA4 pathogenic variants were responsible for 14% of cases in our cohort for a wide variety of IRD phenotypes from AR Stargardt disease to CRD and, in some advanced cases RP27." (PMID 32641690, 2020). "In this study, we evaluate retinal sublayer changes as measured by OCT in a large cohort of patients with molecularly-confirmed ABCA4-associated Stargardt disease." (PMID 33024232, 2020). "Stargardt disease (STGD1) is an autosomal recessive disorder caused almost exclusively by variants in the ATP-binding cassette subfamily A member 4 (ABCA4) gene (MIM: 601691)." (PMID 31963381, 2020). "The most frequently encountered gene was ABCA4 (causing Stargardt macular dystrophy or cone–rod dystrophy)." (PMID 32423767, 2020). "In this cohort, ABCA4-associated retinal degeneration presented as Stargardt disease 1 (STGD1, 62.16%), retinitis pigmentosa (32.43%), and cone-rod dystrophy (5.41%)." (PMID 33261146, 2020). "A progressive hereditary disease, Stargardt disease, is caused by a mutation in ABCA4, another lipid transporter, which causes blindness due to lipid deposits, lipofuscin, in the RPE86." (PMID 33299105, 2020). "A mutation of ABCA4, encoding the transporter of atRAL to the outside of discs, has been shown to cause Stargardt disease and recessive retinal pigmentosa." (PMID 31357484, 2019). "Overall, we demonstrated that AON-based splicing modulation holds great potential for treating Stargardt disease caused by splicing defects in ABCA4." (PMID 31197102, 2019). "Mutations in the ABCA4 gene cause Stargardt’s disease, a form of autosomal recessive juvenile macular degeneration." (PMID 31739639, 2019). "Microperimetry has also been reported to provide valuable information on macular function in cases of ABCA4-associated retinal degenerative diseases (Stargardt disease and cone-rod dystrophy) and night blindness." (PMID 31245978, 2019). "In humans, the ABCA4 gene is associated with Stargardt disease (STGD), an autosomal recessive retinal degeneration leading to central visual impairment." (PMID 30889179, 2019). "Stargardt disease is the most common hereditary macular dystrophy caused by recessive mutations in the ABCA4 gene." (PMID 31739639, 2019). "Overall, our results show that AON-based splicing modulation holds great potential for treating Stargardt disease caused by splicing defects in ABCA4." (PMID 31197102, 2019). "Our study further expands the mutation spectrum in the exonic and flanking regions of ABCA4 underlying Stargardt disease." (PMID 30060493, 2018). "Additional diseases were also linked to mutations in ABCA4 including fundus flavimaculatus, cone-rod dystrophy (CRD), and retinitis pigmentosa or variants considered as a risk factor for age-related macular degeneration." (PMID 29736279, 2018). "Here we report novel mutations in ABCA4 with the underlying phenotype in a large French cohort with autosomal recessive Stargardt disease." (PMID 30060493, 2018).